RB1 (RB transcriptional corepressor 1)
Diseases named in the same sentence as RB1 in open-access papers (continued):
Sharing a sentence is not in itself a finding about the gene and the disease.
lung carcinoma (174 papers, 1997 to 2026). "RB1 downregulation in NCI-H2030 lung cancer cells was associated with an increase in phosphorylation of RPA32 and increased sensitivity to navitoclax." (PMID 40436896, 2025). "RB1 (RB transcriptional corepressor 1) restrains G1–S transition by repressing E2F; its loss in lung cancer induces proliferation, promotes genomic instability, and fuels aggressive behavior." (PMID 41154602, 2025). "The authors demonstrated a correlation between multiple genetic alterations, such as aberrant expression of FAT1, deletion of RB1, loss of the long (q) arm of chromosome 5, and lung cancer." (PMID 38539567, 2024). "Gene mutations in RB1 gene were associated with shorter overall survival in bladder, glioma and lung cancers." (PMID 39277826, 2024). "LUAD samples, lung squamous cell carcinoma (LUSC) samples, and lung cancer cell lines with RB1 mutations showed significantly lower expression of RB1 and encoded proteins than cell lines with WT RB1." (PMID 37937640, 2023). "RB1-deficient non–small cell lung cancers, compared with their RB1-proficient counterparts, showed efficient and prolonged responses to chemotherapy." (PMID 37183818, 2023). "The retinoblastoma susceptibility gene (RB1) is a known tumor suppressor gene involved in lung cancer development." (PMID 35634240, 2022). "In this study, we concluded that age and PLTs were independent risk factors for bone metastasis of lung cancer, respectively, and there were more RB1 gene mutations in bone metastasis and less tumor heterogeneity in the PLT‐H group." (PMID 34799997, 2022). "Mutational inactivation of the RB1 gene is an oncogenic factor in various cancers, including lung cancer." (PMID 34799997, 2022). "Subsequent studies have found that loss of RB1 renders lung cancer cells suspectable to microtubule destabilization due to overexpression of STMN1, a microtubule depolymerizing protein." (PMID 36372230, 2022). "Another study, however, found that RB1 mutations were higher in African Americans than in European Americans in patients with lung cancer." (PMID 36466542, 2022). "Acquired resistance to MEK inhibition in lung cancer has previously been associated with p16/RB1/CDK4 regulatory status." (PMID 36418460, 2022). "It is possible that RB1 loss in EGFR mutant lung cancer cells will yield a similar, synthetically lethal interaction with these inhibitors." (PMID 32292420, 2020). "RB1 mutational inactivation is a cancer driver in various types of cancer including lung cancer, making it an important target for therapeutic exploitation." (PMID 33037191, 2020). "Our lung cancer cell panel analysis also showed that cells with RB1 loss expressed high level of stathmin and were associated with unbalanced microtubule dynamics compared to those expressing wildtype RB1." (PMID 33037191, 2020). "The loss of Rb1 accelerates lung tumor progression in mutant Kras-driven lung cancer in vivo, resulting in the development of higher grade adenocarcinomas and decreased overall survival." (PMID 31963621, 2020).
lung carcinoma (continued). "This study provides strong evidences to support the model that AURKA inhibition promotes the stathmin activity, resulting in the disruption of microtubule dynamics, which sensitizes RB1-deficient lung cancer cells to mitotic cell death." (PMID 33037191, 2020). "Based on our findings, we suggest that upstream factors regulating microtubule dynamics are promising drug targets in lung cancer cells with RB1 loss-of-function mutations." (PMID 33037191, 2020). "Consistent with previous findings, loss of Rb1 significantly decreased overall survival and increased tumor burden in this Kras-driven lung cancer model." (PMID 31963621, 2020). "Mutation in RB1 gene losses the activation, prevents cells from S phase, and leads to the occurrence of lung cancer." (PMID 32508051, 2020). "Here, we report that loss of the gene encoding pRb (Rb1) in a transgenic mutant Kras-driven model of lung cancer results in metabolic reprogramming." (PMID 31963621, 2020). "Here the authors perform chemical and genetic vulnerability screens and identify aurora A kinase (AURKA) as a synthetic lethal candidate for RB1-deficient lung cancer cells and that AURKA inhibition sensitizes these cells to mitotic cell death." (PMID 33037191, 2020). "We here report that AURKA is amongst the strongest synthetic lethal candidate for RB1 deficiency in lung cancer cells." (PMID 33037191, 2020). "The different outcomes of RB1 mutation observed among lung cancer subtypes suggest a more complicated mechanism than simple regulation of cell cycle or response to chemotherapy." (PMID 30773851, 2019). "Lung cancer is the leading cause of cancer deaths and is associated with p16/RB1 pathway deregulation." (PMID 28414317, 2017). "In the current study, genetically engineered mouse models were used to determine the regulation and biologic significance of p16 induction in RB1-deficient lung epithelial cells that give rise to lung cancer; a common epithelial derived malignancy." (PMID 28414317, 2017). "The RB1 independent tumor suppressive functions of p16 are physiologically relevant in vivo as demonstrated by the development of aggressive lung cancers upon p16 loss in RB1-deficient lungs of genetically engineered mouse models." (PMID 28414317, 2017). "While mutations in the retinoblastoma (RB1) tumor suppressor have been reported in lung cancer, mainly in small cell lung carcinoma, the tumor suppressive role of its relatives p107 and p130 is still a matter of debate." (PMID 27966456, 2017). "Other losses associated with cluster B2 were located on 13q and included RB1, which is frequently altered in lung cancer, and three other tumor suppressor genes." (PMID 21151896, 2010). "Thus, RB1 inactivation is predictive of the risk of LUAD transforming into more aggressive lung cancer types." (PMID 40847555, 2025). "Accordingly, AURKA inhibition in RB1-deficient lung cancer is synthetically lethal." (PMID 39334449, 2024). "In addition, Aurora kinase A and B inhibition is synthetically lethal in combination with RB1 loss in breast and lung cancer cells." (PMID 38837893, 2024).
lung carcinoma (continued). "Based on the systematic screening of genomic variations that have SL interactions with PARPis, we found that RB1 mutation may mediate sensitivity to PARPis in lung cancer cells." (PMID 37937640, 2023). "Moreover, we screened RB1 gene mutations by characterizing different subgroups of lung cancer bone metastases." (PMID 34799997, 2022). "Herein, more presence of RB1 gene mutations in bone metastases of lung cancer was correlated to the worse prognosis of patients, and RB1 mutations may lead to tumor differentiation and growth and promote tumor metastasis." (PMID 34799997, 2022). "Finally, a prior publication showed that upregulation of the microtubule depolymerizing protein Stathmin 1 (STMN1) in RB1 deficient lung cancer cells created synthetic lethality with AURKA inhibition." (PMID 36372230, 2022). "Moreover, AK-01 has more potent anti-tumor activities in MCC-9 xenografts, which is consistent with the notion that AURKA inhibitor retained synthetic lethality in cancer cells with RB1 loss in lung cancers." (PMID 34359608, 2021). "Retinoblastoma susceptibility gene (RB1) is frequently mutated in lung cancers." (PMID 33037191, 2020). "We anticipate analogous results may be obtained in EGFR-mutant lung cancers that lose RB1 since these variants are likely to up regulate EZH2." (PMID 32292420, 2020). "For cases also harboring homozygous mutated genes, it seems that the presence of the genetic variant is more influential than the parent-of-origin of the cnnLOH, with the exception that RB1, in which all lung cancer cell lines (7/7) are associated with hypermethylation at the RB1 imprinted DMR." (PMID 28883545, 2017). "Thus, we systematically explored candidate responsive biomarkers for PARPis based on genetic interactions by utilizing bioinformatics screening, and revealed that mutation of retinoblastoma tumor suppressor gene (RB1) is a candidate PARPi-sensitive biomarker for lung cancer." (PMID 37937640, 2023). "In addition, RB1 mutations combined with CDK4/6 deficiency had synthetic viable effect in lung cancer cells, which indicates that the lung cancer patients with RB1 mutations could not be suggested to use Palbociclib." (PMID 36180906, 2022). "Additionally, acute loss of Rb1 increases mitochondrial pyruvate oxidation in normal lung tissue; however, the metabolic effects of Rb1 loss during lung cancer development are largely unknown." (PMID 31963621, 2020). "Targeted therapeutic strategies aimed at these critical nodes, such as inhibiting CDK4 or cyclin D1 activity or restoring RB1 function, are expected to offer new therapeutic avenues for lung cancer patients." (PMID 40568194, 2025).
lung carcinoma (continued). "Taken together, these results prompted us to conjecture that the immune cells (e.g., macrophages, T cells, NK cells, DCs, and B cells) are recruited to the surface of RB1-mutant lung cancer cells." (PMID 37937640, 2023). "Total HMT expression was significantly up-regulated in RB1-mutant lung cancer cell lines relative to wild-type RB1 cell lines (2-way ANOVA controlling for lung cancer subtype, p = 0.034)." (PMID 37883365, 2023). "RB1-mutant lung cancer cells tended to be sensitive to olaparib, niraparib, and talazoparib in the Genomics of Drug Sensitivity in Cancer (GDSC) and the Cancer Therapeutics Response Portal (CTRP) data sets." (PMID 37937640, 2023). "EGFR and RB1, played key roles in cell cycle, functioned in the metastasis and carcinogenesis of head and neck cancer and lung cancer." (PMID 35397555, 2022). "For example, we found RB1 mutation was associated with resistance to Palbociclib, a highly selective inhibitor of CDK4/6, in lung cancer cells." (PMID 36180906, 2022). "Compared to the TCGA data, the Nanjing Lung Cancer Cohort (NJLCC) and CHOICE cohort of Chinese patients revealed higher rates of EGFR and RB1 mutations, and lower rates of KRAS, BRAF, and STK11 mutations, in adenocarcinoma patients." (PMID 34195081, 2021). "Another recent study revealed that intragenic complex rearrangements were related to RB1 inactivation in EGFR-mutant lung cancer cell." (PMID 34271921, 2021). "AURKA siRNA and small molecule AURKA inhibitors, including ENMD-2076, Aurora A inhibitor I, and alisertib, induced selective toxicity in RB1−/− lung cancer cells." (PMID 34050264, 2021). "All three AURKA inhibitors showed strong antitumor effects on RB1−/− lung cancer xenografts in mice, while RB1+/+ tumors were much less sensitive to the inhibitors." (PMID 34050264, 2021). "Another study using an RNAi library in RB1-knockout lung cancer cells identified Aurora A and reasoned its mechanism by E2F-mediated upregulation of microtubule destabilizer Stathmin/OP18." (PMID 34359636, 2021). "Aurora A inhibition activated Stathmin through reduction of its phosphorylation, inducing mitotic cell death in RB1-knockout lung cancer cells." (PMID 34359636, 2021). "Alisertib and Aurora A Inhibitor I also showed selective antitumor effects on RB1−/− lung cancer xenografts." (PMID 33037191, 2020). "We next tested AURKA inhibition in a panel of lung cancer cell lines with different RB1 status and found that the synthetic lethal effect appeared in general in RB1-mutant, SCLC cell lines." (PMID 33037191, 2020). "In lung cancer, NcRNA-RB1, a lncRNA expressed from the RB1 promoter, inhibits the expression of CALR." (PMID 33194608, 2020).
lung carcinoma (continued). "It is known that RB1 is a tumor suppressor and is frequently inactivated in many cancers, including lung cancer." (PMID 31217907, 2019). "In summary, inhibitors of CDK4/6 sensitize lung cancer cells to oxidative stress-inducing anticancer drugs by creating a functional link between RB1, PARP1, and OGG1." (PMID 29306194, 2018). "Aberrant RB1 expression are known to promote occurrence of lung cancer, but the relationship with invasion process like EMT and underlying mechanism are not well interpreted yet." (PMID 28716024, 2017). "Nevertheless, frequent disruption of the CDKNA2 locus in SQCC significantly increases the involvement of RB1-mediated pathways in this type of lung cancer." (PMID 24722523, 2014). "The miR-17 family (in an FFL with the E2F1and the RB1) was found to be an important family in the lung cancer regulation network." (PMID 24200043, 2013). "This study was carried out to examine cyclin D1 (CCND1) and retinoblastoma (RB1) gene expression in the bronchial epithelium of patients with lung cancer." (PMID 9192978, 1997). "In the context of epigenetic initiation, different histological types of lung cancer each exhibit distinct genomic characteristics, such as RB1 and MYC alterations in SCLC, NFE2L2, TP63 and NOTCH1 variations in LUSC, and EGFR, KRAS and ERBB2 variations in LUAD." (PMID 40847555, 2025). "In this study, whether the effect of RB1 is dose dependent in lung cancer cells warrants future detailed research." (PMID 37937640, 2023). "To test this hypothesis, we generated an RB1-KO cell line from RB1-WT A549 lung cancer cells using the CRISPR/Cas9 system." (PMID 37937640, 2023). "In addition, miR-192 can target the RB1 gene to induce lung cancer cell apoptosis through the caspase pathway." (PMID 35954205, 2022). "In the kras‐driven lung cancers, loss of RB1 promotes a glycolytic phenotype but does not alter pyruvate oxidative metabolism or glutamine inactivation." (PMID 34799997, 2022). "RB1 can interacts with E2F1 to regulate EMT related proteins in lung cancer." (PMID 35969010, 2022). "Herein, we report that loss of Rb1 in a mutant Kras-driven model of lung cancer enhances glycolytic metabolism without altering mitochondrial pyruvate oxidation." (PMID 31963621, 2020). "In order to examine whether the reduced α-tubulin stability in RB1−/− cells was due to the reduced microtubule polymerization in the cells, we analyzed the polymerization status of microtubules in the RB1-isogenic lung cancer cell pairs." (PMID 33037191, 2020).